PRL (prolactin)
Diseases named in the same sentence as PRL in open-access papers (continued):
Sharing a sentence is not in itself a finding about the gene and the disease.
hyperprolactinemia (continued). "Hyperprolactinemia is commonly defined as the condition of a sustained increase in PRL up to that of a fasting level (at least 2 h after waking) of above 20 ng/mL (~424 mIU/L) in men, and above 25 ng/mL (~530 mIU/L) in women." (PMID 36313772, 2022). "Hyperprolactinemia was present in 11 of 50 patients at the beginning; however, normal serum PRL levels were achieved in all patients after cabergoline treatment." (PMID 35612842, 2022). "Hyperprolactinemia is another reproductive endocrine disease characterized by high level of serum prolactin (PRL) and hypogonadotropic anovulation which leads to infertility." (PMID 35837314, 2022). "In this context, it has been shown that higher than-normal serum concentrations of PRL (hyperprolactinemia) lead to insulin resistance and glucose intolerance." (PMID 36471299, 2022). "The incidence rates of akathisia, somnolence, hyperprolactinemia, increase in blood prolactin, tremor, and dystonia were relatively high in the pooled blonanserin group compared with those in the placebo group." (PMID 35133884, 2022). "For most patients with prolactinomas, regular use of DAs can significantly reduce tumor volume and PRL levels, and significantly improve the symptoms of hyperprolactinemia and tumor mass compression." (PMID 35741585, 2022). "Thereby, prolactin levels are the most important predictors at early follow-up, both for the control of hyperprolactinemia and for dependence on DAs." (PMID 35250868, 2022). "In this regard, several reports have revealed that adjunctive metformin significantly reduces PRL levels in patients with antipsychotic-induced hyperprolactinemia." (PMID 35820883, 2022). "Progestin induces hyperprolactinemia, similar to anti-dopamine antagonists, and increases PRL levels via decidualization of the endometrium." (PMID 35820883, 2022). "In one study which sampled at 30 min intervals for 2 h, 61% of women with hyperprolactinemia on two previous independent samples obtained via venepuncture had normal serum prolactin." (PMID 36013562, 2022). "A young woman presented with secondary amenorrhea and was found to have significant hyperprolactinemia (serum prolactin 203 ng/ml)." (PMID 35608811, 2022). "For example, in female rats, drug-induced hyperprolactinemia, or 10-day prolactin administration, as well as ectopic pituitary transplants, increase food intake and body weight." (PMID 35757410, 2022). "The role of PRL in RA remains poorly defined but hyperprolactinemia is emerging as a protective influence." (PMID 35721729, 2022). "The average age was 61.68 ± 11.72 years old; 26.9% of them had osteoporosis (OS) while the prevalence of OS was 17.6% in men and 41.25% in women; 15.8% of them had a mild increase in PRL and the rate of hyperprolactinemia was 18.6% in men and 11.5% in women." (PMID 36313749, 2022). "Another study showed, that when cabergoline was used to lower prolactin in patients with hyperprolactinemia, this improved cognitive function." (PMID 36581642, 2022). "While physiologic levels of PRL increased cytotoxic activity, higher concentrations, compatible with hyperprolactinemia, significantly suppressed it." (PMID 36389803, 2022). "Recoveries of PRL levels <40% are indicative of predominance of macroprolactin, whereas recoveries >60% point to the diagnosis of monomeric hyperprolactinemia." (PMID 35000899, 2022). "Premenopausal women have physiologically higher levels of prolactin compared to men and are therefore closer to the threshold for hyperprolactinaemia (Kaar, Natesan, McCutcheon, & Howes, 2020; Riecher-Rössler, 2017)." (PMID 34763737, 2022). "Hyperprolactinemia promotes the conversion of PRL to vasoinhibin by providing more substrate to cleaving proteases." (PMID 35721729, 2022). "Serum prolactin was lower in group I, with 35.7% of patients having hyperprolactinemia and 10.3% of patients having hypoprolactinemia." (PMID 34276556, 2021).
hyperprolactinemia (continued). "Heterogeneity has been described in the molecular size of prolactin in the majority of serum samples from healthy individuals and patients with hyperprolactinemia." (PMID 34620143, 2021). "The normalization of serum PRL levels is therefore recommended for restoration of male sexual desire in patients with hyperprolactinemia and dopamine agonists (bromocriptine and cabergoline) are the first choice, especially for prolactinomas." (PMID 34207687, 2021). "When investigating the etiology of hyperprolactinemia, clinicians need to be aware of several conditions that can influence PRL measurement leading to misdiagnosis and, consequently, to inappropriate patient management." (PMID 32949349, 2021). "The authors identified that prolactin serum levels and the presence of hyperprolactinemia were higher in females with chronic migraine than those with episodic migraine." (PMID 34737888, 2021). "A prolactin-secreting leiomyoma should be considered in patients with hyperprolactinaemia and normal pituitary MRI which is refractory to dopamine receptor agonist therapy who also have evidence of a uterine fibroid." (PMID 34540295, 2021). "Pathophysiological reasons for the association between prolactin and metabolic parameters include a possible direct effect of prolactin on adipose tissue, hyperprolactinaemia-triggered hypogonadism and dopamine-agonist therapy per se." (PMID 33902531, 2021). "Serum concentration of 9-hydroxyrisperidone was predominantly related to increased PRL levels, especially in autistic patients with hyperprolactinemia during risperidone treatment." (PMID 34867511, 2021). "Prolactin levels were higher in women and patients with mUPD, with only 3 patients having severe hyperprolactinemia." (PMID 34441908, 2021). "Guideline for hyperprolactinemia has defined the DAs resistance as a failure to achieve normal PRL levels together with a ≥ 50% reduction in tumor size at maximally tolerated doses." (PMID 35095761, 2021). "Hyperprolactinemia (HPRL) is caused by a variety of factors and characterized by the significant elevation of serum prolactin (PRL)." (PMID 34424219, 2021). "Hyperprolactinaemia is also a common finding in patients with macroprolactin as the dominant form of prolactin." (PMID 33635916, 2021). "In such a scenario, prolactin has been proven to be responsible for growth and differentiation on porcine mammary epithelium, with late gestational hyperprolactinemia leading to enhanced lactogenesis and milk production without altering vascular development." (PMID 33808012, 2021). "One female patient presented a higher value of prolactin; nevertheless, she was in the postmenopausal period, whereas a mild hyperprolactinemia was observed in 7 out of 16 male subjects." (PMID 35211089, 2021). "Firstly, a broad forebrain neuron-specific deletion of Prlr using the Prlrlox/lox/Camk2aCre mouse blocked the effect, implicating a prolactin action in the brain, but this model was complicated by hyperprolactinemia and abnormal estrous cycles." (PMID 34528511, 2021). "Although prolactin elevation is usually mild (25–100 ng/mL), in cases of drug-induced hyperprolactinemia, it is also highly variable." (PMID 33768297, 2021). "The reported prevalence of hyperprolactinemia in patients on risperidone ranges between 44 and 61%, and abnormal prolactin levels occur in about 27% of patients taking risperidone." (PMID 34690776, 2021). "Despite not staining for prolactin, quick resolution of the patient's hyperprolactinaemia after myomectomy supports the diagnosis of a prolactin-secreting fibroid." (PMID 34540295, 2021). "First, in hyperprolactinemia, headaches with migraine characteristics have been described and normalization of the prolactin level has alleviated headaches." (PMID 34737888, 2021). "Hyperprolactinemia was diagnosed in 207 patients (39.1%), and 90 (43.5%) of them had prolactin-positive adenomas." (PMID 35154007, 2021).
hyperprolactinemia (continued). "There have also been multiple studies which have shown that the prolactin concentration is related to size of tumour and all patients with sustained hyperprolactinaemia go on to have pituitary imaging." (PMID 33963239, 2021). "The strength of the study is the careful evaluation of all patients with hyperprolactinemia and the use of the same method for analysis of prolactin in all countries." (PMID 34441908, 2021). "Monomeric prolactin concentration, along with a reference interval screening with PEG precipitation, provides a diagnostic approach for hyperprolactinemia with improved accuracy." (PMID 34620143, 2021). "Hyperprolactinemia is defined as sustained levels of prolactin above the laboratory upper limit of normal." (PMID 34441908, 2021). "Of the 65 participants who had thyroid-stimulating hormone (TSH) assessment 13 (20%) had elevated levels while out of the 81 who had prolactin measurement 11 (13.6%) had hyperprolactinaemia." (PMID 35096218, 2021). "In our study, the mean prolactin level was 25.3 ± 22.5 ng/ml in all subjects and 51.6% of participants had hyperprolactinemia." (PMID 34421613, 2021). "In hyperprolactinemia, excess prolactin leads to inhibition of the gonadotropin-releasing hormone (GnRH) from the hypothalamus." (PMID 33946142, 2021). "Despite prolactin levels were similar in both groups, as well as the prevalence of subjects who took medications affecting prolactin secretion, the prevalence of severe hyperprolactinemia was significantly higher in men requested to perform a MRI." (PMID 33970435, 2021). "While the prolactin levels in most patients with hyperprolactinemia returned to normal after surgery, hyperprolactinemia remained in 10 patients (1.9%)." (PMID 35154007, 2021). "Total prolactin was significantly higher (p < 0.001) in patients with true hyperprolactinemia compared to patients with macroprolactinemia, and this difference was maintained after treatment of serum with PEG." (PMID 34620143, 2021). "Mammosomatotroph tumors resemble densely granulated somatotroph tumors in all aspects, but in addition, they express prolactin and give rise to significant hyperprolactinemia." (PMID 34067494, 2021). "• The prolactin level of patients was 18.9.• The frequency of hyperprolactinemia in patients was 20%." (PMID 34447911, 2021). "An elevated titer of aTPO and/or aTG was slightly more common in patients with hyperprolactinemia than in patients with normal prolactin concentration: 47.4% and 42.9%." (PMID 33671229, 2021). "It is proven in a long-term study that risperidone treatment induced PRL increase and hyperprolactinemia." (PMID 34867511, 2021). "Patients with preoperative hyperprolactinemia had a higher recurrence rate and shorter median recurrence time after surgery than those with normal prolactin (HR, 1.39 (1.08-1.79); log-rank p=0.012]." (PMID 35154007, 2021). "As DAs can be tapered 24 months after initiation of medical therapy when prolactin (PRL) levels are normalized, early recurrence of hyperprolactinemia following discontinuation of DAs have been reported, particularly in patients with macroprolactinomas." (PMID 34054739, 2021). "Hyperprolactinemia was suspected to be secondary to prolactin cosecretion in 3 of the 15 presenting with hyperprolactinemia (20%) and stalk effect in the other 12 (80%)." (PMID 34867787, 2021). "In schizophrenics, hyperprolactinemia occurs as PRL increases estrogen which induces more production of PRL." (PMID 33995058, 2021). "PRL was first noted in ccRCC as a result of a case report in which physicians accidentally found a kidney cancer patient with hyperprolactinemia, and their prolactin levels returned to normal after tumor resection." (PMID 34539753, 2021). "Our case also showed occasional elevated PRL, and previous studies also found that a small number of patients will have galactorrhoea or hyperprolactinemia." (PMID 34248835, 2021).
hyperprolactinemia (continued). "Previous studies showed that use of antipsychotics has been associated with hyperprolactinemia (HPRL) and that PRL abnormality can affect metabolic and reproductive functions and endocrine systems in vivo." (PMID 32788631, 2020). "Some results are Parkinson’s Disease, Seborrheic dermatitis, Hepatic Encephalopathy, Hepatic Coma, Hypotension, Secondary hyperprolactinemia due to prolactin-secreting tumor, Striatonigral Degeneration, nervous system disorder, and Hypokinesia." (PMID 33317518, 2020). "Prolactin levels over 250 ng/mL are highly indicative for prolactinomas, while drug-induced hyperprolactinemia doesn’t usually exceed 100 ng/mL." (PMID 32017792, 2020). "In our study, before treatment, progesterone level was decreased in women with idiopathic hyperprolactinemia, and after normalization of PRL level, there was a significant increase in its level." (PMID 33426414, 2020). "Macroprolactinemia is mostly defined as a type of hyperprolactinemia where more than 60% of circulating PRL is made up of macroprolactin." (PMID 32597541, 2020). "The hyperprolactinemia that is also encountered in the GhrhrGpr101 mice requires specific studies to determine the precise mechanisms by which PRL dysregulation occurs and how this impacts the phenotype of these animals." (PMID 32958754, 2020). "Only 37 participants had prolactin measured, where four males (15%) and six females (55%) exceeded the prolactin threshold for hyperprolactinemia." (PMID 33329382, 2020). "According to our study, the timing of normalization of blood PRL levels in women with idiopathic hyperprolactinemia almost coincides with the timing of menstrual cycle regulation (two-five months) and ovulation is restored later (three-seven months)." (PMID 33426414, 2020). "Dopamine acts by inhibiting prolactin; therefore, antipsychotic medications, blocking the D2 receptor via the tuberoinfundibular pathway, lead to hyperprolactinemia." (PMID 33343407, 2020). "Female gender, antipsychotic medication according to the potency of inducing hyperprolactinemia, and the duration of psychosis over 10 years appear to influence prolactin serum levels." (PMID 32017792, 2020). "There are three types of hyperprolactinemia: mild hyperprolactinemia, where PRL level varies from 25-50 ng/ml, moderate hyperprolactinemia, where PRL level is between 50 and 100 ng/ml, and higher PRL levels > 100 ng/ml." (PMID 33426414, 2020). "Dopamine agonists are widely used for suppression of serum PRL and resumption of ovulation in infertile women with hyperprolactinemia seeking to conceive naturally." (PMID 32982975, 2020). "The higher the post‐PEG PRL recovery rates, the less typical hyperprolactinemia symptoms and the higher prevalence of autoantibodies were observed." (PMID 32597541, 2020). "Four studies showed an increase in serum prolactin levels among patients on opioid analgesics, whereas another study reported that 40% of patients (n = 8) had hyperprolactinemia, and all other patients had normal prolactin levels." (PMID 31511863, 2020). "The primary regulator for PRL pituitary secretion is dopamine via hypothalamic inhibitory signals, and this constitutes the pharmacological basis for hyperprolactinemia treatment." (PMID 32982975, 2020). "The most frequently reported drug-related TEAEs in ≥2% of patients on placebo were dizziness and headache, whereas in both Risperidone ISM® groups (75 and 100 mg) were blood prolactin increase, hyperprolactinaemia, akathisia, and headache." (PMID 33239746, 2020). "Pharmacological treatment strategies for lowering prolactin in people with a psychotic disorder and hyperprolactinaemia: a systematic review and meta-analysis." (PMID 32642517, 2020). "Hyperglycemia has been demonstrated in men and women with hyperprolactinemia due to the direct effects of prolactin on Langerhans islet growth and insulin production." (PMID 32655635, 2020).
hyperprolactinemia (continued). "Patients treated with prolactin raising antipsychotics presented significantly more frequent hyperprolactinemia than those treated with prolactin sparing antipsychotics (p = 0.004)." (PMID 32017792, 2020). "In our study, continuous treatment with dopamine agonist in women with idiopathic hyperprolactinemia led to the PRL level normalization, menstrual cycle regulation, and occurrence of pregnancy in all cases." (PMID 33426414, 2020). "Patients in early remission at 3 months had lower serum prolactin concentrations on the first postoperative day than patients with recurrent or persistent hyperprolactinemia (p < 0.001)." (PMID 32733387, 2020). "The most frequently reported treatment-emergent adverse events were increased blood prolactin (7.8%), headache (7.3%), hyperprolactinemia (5%), and weight increase (4.8%)." (PMID 33239746, 2020). "In rodents, hyperprolactinemia has been reported to correlate with increased mammary tumorigenesis, and PRL administration has been shown to promote mammary tumorigenesis or tumor growth." (PMID 33162942, 2020). "Another retrospective study indicated that normalization of prolactin occurred in 87% of patients with microadenomas and in 56% of macroadenomas after surgery, and recurrence of hyperprolactinemia occurred in 13% of them at 10 years follow-up." (PMID 31191457, 2019). "Recent data expand the biological effects of prolactin particularly on metabolism, cancer, cardiovascular and immune systems opening new avenues on the clinical implications of prolactin and the consequences of hyperprolactinaemia." (PMID 31847209, 2019). "Recovery of free PRL > 60% of the total is suggestive of monomeric hyperprolactinaemia, whereas recovery <40% is consistent with macroprolactinaemia." (PMID 31847209, 2019). "Another way to explain hyperprolactinemia is the ability of antipsychotic-drugs to cross the blood-brain barrier and to affect the activity of prolactin-inhibiting and prolactin-stimulating factors." (PMID 30967134, 2019). "The therapeutic targets in prolactinomas are to normalize PRL, reduce tumour size, resolve clinical manifestations of hyperprolactinaemia and of mass effects (particularly visual disturbances) and prevent progression or recurrence of the tumour." (PMID 31847209, 2019). "Large pituitary macroadenomas (>3 cm with expected PRL level >10,000 μg/L) with only mild hyperprolactinaemia should raise suspicion for the hook effect, and close interaction between clinicians and biochemists is required in this scenario." (PMID 31847209, 2019). "PRL within the physiological range stimulates bone formation, mild hyperprolactinaemia increases bone resorption, and marked hyperprolactinaemia further increases bone resorption and inhibits bone formation." (PMID 31847209, 2019). "An excessive rise in prolactin or hyperprolactinemia is a common endocrinological disorder in hypothalamic-pituitary region which affects the reproductive function in both sexes." (PMID 32641968, 2019). "Patients with asymptomatic hyperprolactinaemia due to antipsychotics should undergo periodic monitoring of PRL, as well as regular clinical assessments for relevant manifestations." (PMID 31847209, 2019). "Hyperprolactinemia was found to be present in Case 2, whereas Case 1 (a 49-year-old woman) had "normal" serum prolactin levels for premenopausal and prolactin levels slightly above the maximum levels for postmenopausal women." (PMID 31417404, 2019). "For microprolactinomas, PRL is usually 100 to 200 μg/L, however, outliers exist; in the Brazilian Multicenter Study on Hyperprolactinaemia which included 444 patients with microprolactinoma, mean PRL was 165 μg/L but ranged from 32 to 525 μg/L." (PMID 31847209, 2019). "Four (11.1%) boys had hyperprolactinemia (617.2; 604.6; 567.4 and 381.6 mIU/L) and one patient had a history of galactorrhoea concurrent with normal PRL level." (PMID 31117335, 2019).